PCNA (proliferating cell nuclear antigen)
Diseases named in the same sentence as PCNA in open-access papers (continued):
Sharing a sentence is not in itself a finding about the gene and the disease.
Hypokalemia (1 paper, 2022). An abnormally decreased potassium concentration in the blood. "Sections from a previous study, in which mice had developed frank hypokalemia in response to 6 days aldosterone infusion, were fluorescence-labeled with NCC (DCT cell marker) and the proliferation marker, PCNA." (PMID 35557966, 2022). "To study the effects of aldosterone on PCNA expression in the DCT in a condition without hypokalemia, we labeled sections from mice that had been infused with amiloride + aldosterone or fed a low K+ diet for 6 days (Protocol 3)." (PMID 35557966, 2022). "As hypokalemia can enhance cell proliferation markers in the distal convoluted tubule (DCT), we hypothesized that aldosterone infusion would increase proliferating cell nuclear antigen (PCNA) expression." (PMID 35557966, 2022).
Hyponatremia (1 paper, 2023). An abnormally decreased sodium concentration in the blood. "The expression of PCNA, which is a nuclear protein involved in DNA replication, elongation and repair, was reduced in the testes of mice with hyponatremia." (PMID 36436190, 2023).
hypopharyngeal carcinoma (1 paper, 2024). Carcinoma, predominantly squamous cell, arising from the epithelial cells of the hypopharynx. "In hypopharyngeal carcinoma, the protein expression levels of PCNA and Ki-67 were higher than those in the control group, with a significantly increased H-score (p < 0.05)." (PMID 39472448, 2024).
idiopathic dilated cardiomyopathy (1 paper, 2023). Decreased function of the heart associated with cardiac enlargement and congestive heart failure, of unknown cause. "Increased expression of the DNA repair proteins PCNA, DNA‐PKcs, and APE1 is correlated with left ventricular dysfunction in patients with idiopathic dilated cardiomyopathy, suggesting increased DNA repair activity in diseased cardiac tissue." (PMID 36734200, 2023).
immunoglobulin deficiency (1 paper, 2023). "For instance, aside from the mild immunoglobulin deficiency seen in patients expressing PCNA-C148S, patients with PARD generally do not have significant immunologic dysfunction." (PMID 36990216, 2023).
immunotoxicity (1 paper, 2025). "It modulated immunotoxicity, oxidative stress, and hepatorenal damage, and increased caspase-3 immunopositive splenocytes and proliferating cell nuclear antigen (PCNA) levels." (PMID 40308777, 2025).
injury (1 paper, 2020). Damage inflicted on the body as the direct or indirect result of an external force, with or without disruption of structural continuity. "In the current study, we demonstrated that late treatment (12 h after APAP administration) with Mito-T did not inhibit PCNA expression following APAP-induced liver injury." (PMID 33050213, 2020).
intracranial hypertension (1 paper, 2017). A finding characterized by increased cerebrospinal fluid pressure within the skull. "The results demonstrated that intracranial hypertension increased the apoptosis rate, caspase-3 levels and proliferating cell nuclear antigen (PCNA) in the hippocampus, hypothalamus, pituitary gland and showed a consistent rate of apoptosis within each group." (PMID 28630478, 2017).
kidney injury (1 paper, 2025). Trauma to the kidney. "In conclusion, this study highlights the role of meprin β activity in regulating cellular proliferation through PCNA regulation, driven by the IL-6-mediated AKT/ERK signaling pathway during the recovery phase following IR-induced kidney injury." (PMID 39975921, 2025).
lactic acidosis (1 paper, 2010). Metabolic acidosis characterized by the accumulation of lactate in the body. "Among clusters of genes repressed by lactic acidosis in the later time points is a large group whose expression is closely linked to cell proliferation (cyclin D, PCNA, CCRK, E2F3, and E2F6)." (PMID 20844768, 2010).
laryngeal squamous cell carcinoma (1 paper, 2013). A squamous cell carcinoma that arises from the larynx. "Up to now, the role of HPV in laryngeal squamous cell carcinoma (LSCC) has not been clearly established, and the correlation between HPV and PCNA in LSCC remains poorly explored." (PMID 24353714, 2013).
leukopenia (1 paper, 2022). "The anti-DFS70-positive patients also had a higher frequency of anti-nRNP/Sm and anti-PCNA, and they were more likely to be accompanied by mucosal ulcers and leukopenia." (PMID 36189276, 2022).
Leydig cell tumor (1 paper, 2024). A sex cord-stromal tumor occurring in the testis and rarely in the ovary. "In contrast, Leydig cell tumors (LCTs) and Diffuse Type Seminoma (DSEM) exhibited increased expression of TfR1, along with higher PCNA expression, suggesting a higher iron need for proliferation." (PMID 39272404, 2024).
lipodystrophy (1 paper, 2025). A congenital or acquired disorder characterized by abnormal loss or redistribution of the adipose tissue in the body. "The thickening of the subcutaneous fat layer observed in lipodystrophy may result from increased adipocyte proliferation and differentiation, as indicated by elevated levels of PCNA." (PMID 40011349, 2025).
lipoma (1 paper, 2016). A benign, usually painless, well-circumscribed lipomatous tumor composed of adipose tissue. "In a previous study, the proliferative activity of lipomas was examined by immunohistochemically analyzing the expression of proliferating cell nuclear antigen and Ki-67." (PMID 26885425, 2016).
lubag syndrome (1 paper, 2022). "Moreover, individuals with lubag syndrome/X-linked dystonia of panay have indicated the paucity of the labeling of NPY within the subventricular zone (SVZ), together with a consequential forfeiture of proliferating cell nuclear antigen (PCNA)-representing progenitor cells (PGCs)." (PMID 35562956, 2022).
lung adenoma (1 paper, 2023). A benign, well circumscribed epithelial neoplasm that arises from the bronchus or the lung parenchyma. "PCNA in malignant tumors of the lungs was more prominently stained than in lung adenoma." (PMID 36608059, 2023).
lupus nephritis (1 paper, 2024). Glomerulonephritis in the context of systemic lupus erythematosus. "Compared with normal kidney, USP2-69 expression was elevated in IgAN, lupus nephritis and APGN (acute proliferative glomerulonephritides), which also displayed the higher expression of PCNA (proliferation cell nuclear antigen)." (PMID 38175721, 2024).
mammary adenocarcinoma (1 paper, 2025). "In canine mammary adenocarcinoma, strong PCNA immunoreactivity has been consistently observed, reflecting increased proliferative activity." (PMID 40430573, 2025).
metastatic colorectal cancer (1 paper, 2024). "With an in vitro approach, we demonstrated that the administration of iPolyP induces the expression of PCNA in Caco-2 and in SW620, non-metastatic and metastatic colorectal cancer cell lines, respectively, without altering the TRPM8 levels." (PMID 39409946, 2024).
mixed connective tissue disease (1 paper, 2014). Mixed connective tissue disease (MCTD) is a rare autoimmune disorder that is characterized by features commonly seen in three different connective tissue disorders: systemic lupus erythematosus, scleroderma, and polymyositis. "Anti-RNP antibodies are linked with mixed connective tissue disease (MCTD) and SLE, anti-PCNA antibodies have been described in a variety of SARD." (PMID 24606591, 2014).
mucinous lung adenocarcinoma (1 paper, 2022). "Using the K-M method, MKI67 and PCNA were confirmed as poor prognosis factors in stages I–III invasive non-mucinous lung adenocarcinoma." (PMID 36010686, 2022).
mucoepidermoid carcinoma (1 paper, 2000). A carcinoma morphologically characterized the presence of cuboidal mucous cells, goblet-like mucous cells, squamoid cells, cystic changes, and a fibrotic stromal formation. "The proliferating cell nuclear antigen expression increases with the grade of malignancy in mucoepidermoid carcinoma of salivary glands." (PMID 10810331, 2000). "The correlation between proliferating cell nuclear antigen expression and the histological malignancy grade in mucoepidermoid carcinoma of salivary glands." (PMID 10810331, 2000). "After a comparative study between histological features and immunohistochemical analysis, significant differences were observed (P < 0.01) for low, intermediate and high grades: 16.04%, 26.98% and 56.98% of proliferating cell nuclear antigen expression in mucoepidermoid carcinoma, respectively." (PMID 10810331, 2000).
myelomeningocele (1 paper, 2022). Myelomeningocele is the most severe form of spina bifida. "The proliferation of bladder tissue cells was inhibited, with suppressed PCNA expression in myelomeningocele bladder tissue compared with that in control tissue at the early stage (E16)." (PMID 35756928, 2022).
myocardial hypertrophy (1 paper, 2018). "Boldenone administration induced various histologic cardiac lesions in young male rats: marked myocardial hypertrophy, necrosis, marked interstitial fibrosis, misshapen nuclei, moderate focal hemorrhage, moderate infiltration of leukocytes, and increase in PCNA expression were observed." (PMID 30116498, 2018).
myocardial infarction (1 paper, 2023). Gross necrosis of the myocardium, as a result of interruption of the blood supply to the area, as in coronary thrombosis. "However, neither an increase of ED-1-positive macrophages nor PCNA staining as a marker of cell proliferation revealed interstitial differences among rats after myocardial infarction and controls." (PMID 37082237, 2023).
nevoid basal cell carcinoma syndrome (1 paper, 2018). A rare hereditary disorder due to autosomal dominant transmission with hamartosis characterized by multiple early-onset basal cell carcinoma (BCC), multiple jaw keratocysts and skeletal abnormalities.
nonalcoholic fatty liver (1 paper, 2017). "The faster growth and higher PCNA index of HepG2 in FLM compared to NLM indicated that the ECM of nonalcoholic fatty liver might promote the proliferation of HCC." (PMID 29221151, 2017).
Oral ulcer (1 paper, 2022). Erosion of the mucous mebrane of the mouth with local excavation of the surface, resulting from the sloughing of inflammatory necrotic tissue. "A. maurorum exhibited a potent healing effect in acetic acid-induced oral ulcers in rats by mitigating the release of pro-inflammatory cytokines and improving PCNA expression." (PMID 35161436, 2022).
oropharyngeal squamous cell carcinomas (1 paper, 2020). "In two independent cohorts of serous ovarian carcinomas and oropharyngeal squamous cell carcinomas, stronger IGF1R/PCNA colocalization was significantly associated with a higher overall survival." (PMID 32701997, 2020).
ossifying fibroma (1 paper, 2013). A bone benign neoplasm that is located_in the mouth and results_in an overgrowth of gingival tissue due to irritation or trauma. "Mesquita RA found higher numbers of argyrophilic nucleolar organizer regions (AgNORs) and proliferating cell nuclear antigen- (PCNA-) positive cells in ossifying fibroma than in peripheral ossifying fibroma, indicating higher proliferative activity in ossifying fibroma." (PMID 23365762, 2013).
osteoblastic osteosarcoma (1 paper, 2025). A conventional osteosarcoma characterized by the predominance of osteoid matrix. "In this study we evaluated the immunohistochemical expression of ferritinophagy-related proteins, namely Ferritin Heavy chain (FTH1) and NCOA4, and proliferating cell nuclear antigen (PCNA) in canine normal bone and canine osteoblastic osteosarcoma (COOS) samples." (PMID 40196812, 2025).
ovarian endometriosis (1 paper, 2015). A non-neoplastic disorder characterized by the growth of endometrial tissue in the ovaries. "Ten paraffin-embedded ovarian endometriosis samples were screened for germ cell-specific proteins DDX4 (VASA) and IFITM3, and its relation with stem cell marker OCT4, proliferation marker PCNA and estrogen receptor alpha (ESR1), by immunohistochemistry, immunofluorescence and PCR." (PMID 26446766, 2015).
ovarian epithelial tumor (1 paper, 2025). A benign, borderline, or malignant tumor that originates from the surface epithelium of the ovary. "The frequency of PCNA geneticalterations was highest in ovarian epithelial tumors (>4%)." (PMID 40657100, 2025).
ovarian serous adenocarcinoma (1 paper, 2012). An adenocarcinoma that arises from the ovary and is characterized by the presence of malignant epithelial cells that, in well differentiated tumors, resemble the epithelium of the fallopian tube or, in poorly differentiated tumors, show anaplastic features and marked nuclear atypia. "TgPTTG #434 developed ovarian serous adenocarcinoma with PCNA staining showed 35% positive area and CD31 staining was 2+." (PMID 23164239, 2012).
papillary adenoma (1 paper, 2013). An adenoma characterized by the presence of papillary epithelial patterns. "Heterozygous knockout mice Cx43+/− presented statistically more lung papillary adenomas and with a higher number of cells stained for PCNA than wild-type animals." (PMID 24199196, 2013).
papillary serous adenocarcinoma (1 paper, 2012). "Additionally, 1 out of 20 (5%) of TgPTTG mice developed an ectopic tumor diagnosed as a papillary serous adenocarcinoma that was 75% positive for PCNA and had significant CD31 staining (3+)." (PMID 23164239, 2012).
parasitic infection (1 paper, 2012). "Up-regulation of PCNA, Cyclin D1, A and B1 is related to the regulation of the G1/S and G2/M phases, which were previously reported to increase biphasically after partial hepatectomy and other parasitic infection." (PMID 22253905, 2012).
parathyroid adenoma (1 paper, 2024). "The expression of proliferative cell nuclear antigen (PCNA) was greater in parathyroid glands with high 99mTc-MIBI scores (hyperintense parathyroid adenoma) compared to those with low scores (hypointense parathyroid adenoma)." (PMID 39001288, 2024).
parvovirus infection (1 paper, 2014). "Specifically, parvovirus infection recruits p21 to viral replication compartments within the nuclei, where it is ubiquitinated and degraded in a proliferating cell nuclear antigen (PCNA) dependent manner." (PMID 25314029, 2014).
plaque psoriasis (1 paper, 2020). "Next, we compared the expression of HDAC1, SIRT1, p63, and PCNA in guttate and plaque psoriasis." (PMID 32825671, 2020).
PNS tumor (1 paper, 2010). "PNS tumor samples also clearly show abundant c-Fos and the proliferation marker PCNA immunostaining with a histology resembling Schwann cells." (PMID 20209053, 2010).
polyp (1 paper, 2020). A usually exophytic mass attached to the underlying tissue by a broad base or a thin stalk.
preeclampsia (1 paper, 2014). Preeclampsia is a hypertensive disorder of pregnancy that is characterized by new-onset hypertension with proteinuria presenting after 20 weeks of gestation, and depending on mild or severe forms may initially present with severe headache, visual disturbances, and hyperreflexia. "For example, Flt-1, HtrA, Calretinin, PAI-1 and EGFR were positively and PDEF, Annexin XI, PLGF and PCNA were inversely correlated with the severity of preterm preeclampsia." (PMID 25392996, 2014). "Among 167 proteins tested, the expression of 5 proteins (EGFR, Flt-1, Calretinin, PAI-1 and HtrA) were positively correlated and four proteins (AnnexinXI, PDEF, PCNA and PlGF) were inversely correlated with the severity of preterm preeclampsia (P<0.05, R value≥0.4)." (PMID 25392996, 2014).
prostate adenocarcinoma (1 paper, 2016). "Treatment of androgen-sensitive human prostate adenocarcinoma cells (LNCaP) with WIN-55,212-2 (WIN), the cannabinoid and CB1 agonist, results in a significant decrease in the expression of Proliferating Cell Nuclear Antigen (PCNA), an essential processivity factor for DNA replication." (PMID 27680736, 2016).
Psoriasiform dermatitis (1 paper, 2016). A skin abnormality characterized by redness and irritation, with thick, red skin that displays flaky, silver-white patches (scales). "Topical application of EGCG alleviated psoriasiform dermatitis, improved the skin pathological structure by reduce the expression of epidermal PCNA, promoted the expression of caspase-14." (PMID 27581210, 2016).
retinal degeneration (1 paper, 2022). Degeneration of the retina. "In the rd1 mouse, an animal model of hereditary retinal degeneration, the DNA damage marker 8-hydroxy deoxyguanosine (8-OHdG) and proliferating cell nuclear antigen (PCNA), a marker of DNA repair, can be found in the outer nuclear layer (ONL)." (PMID 36274523, 2022).
rhabdomyolysis (1 paper, 2016). Necrosis or disintegration of skeletal muscle often followed by myoglobinuria. "MS-275, a class I HDAC inhibitor similar to VPA, reduced the expression of PCNA in AKI that is induced by rhabdomyolysis." (PMID 27195290, 2016).
salivary gland cancer (1 paper, 2017). A primary or metastatic malignant neoplasm that affects the major or minor salivary glands. "In addition, cell cycle-regulated proteins including PCNA were found to be prognostic and diagnostic implications of salivary gland cancers." (PMID 28969025, 2017).
schizophrenia (1 paper, 2014). A major psychotic disorder characterized by abnormalities in the perception or expression of reality. "BARD1 signaling pathway contains three under-expressed genes, BARD1, PCNA and UBE2L3, in which UBE2L3 polymorphism is associated with schizophrenia, and polymorphism study reveals that BARD1 is risk allele for schizophrenia." (PMID 25522158, 2014).
Sjogren syndrome (1 paper, 2018). An autoimmune disorder in which immune cells attack and destroy the glands that produce tears and saliva. "Anti-PCNA antibodies are known to occur in Sjogren’s syndrome, but no clinical signs of ocular or oral symptoms were present for this patient." (PMID 30053822, 2018).
skin atrophy (1 paper, 2022). The degeneration and thinning of the epidermis and dermis. "Thus, skin atrophy and cell proliferation returned almost to normal by 15 days after finishing 12 days of FA treatment, although some keratin, keratin-associated genes, and the cell proliferation marker PCNA were more expressed in the FA-treated skin at that point." (PMID 36551249, 2022).
small cell lung carcinoma (1 paper, 2011). Small cell lung cancer (SCLC) is a highly aggressive malignant neoplasm, accounting for 10-15% of lung cancer cases, characterized byrapid growth, and early metastasis. "Similar results were observed in small cell lung cancer NCI-H510A cells in which tetrac blocked thyroid hormone-induced ERK1/2 activation and PCNA expression." (PMID 22132110, 2011).
smooth muscle tumor (1 paper, 2014). A benign or malignant myomatous neoplasm arising from smooth muscle.
soft tissue sarcoma (1 paper, 2017). A malignant neoplasm arising from muscle tissue, adipose tissue, blood vessels, fibrous tissue, or other supportive tissues excluding the bones. "The immunoreactivity of proliferation markers: the Ki-67 antigen and proliferating nuclear cell antigen (PCNA) was assessed, as it has a good prognostic value for chemotherapy response in various tumors (e.g. human and canine mammary tumors, human soft tissue sarcoma, feline lymphoma)." (PMID 28651614, 2017).